IGF2 (insulin like growth factor 2)
Diseases named in the same sentence as IGF2 in open-access papers (continued):
Sharing a sentence is not in itself a finding about the gene and the disease.
tumor (continued). "IGF1R together with IGF2 may form a short, very active, autocrine loop that is greatly responsible for tumour genesis, as well as intensive proliferation and progression of RMS." (PMID 28793874, 2017). "Thus, together with its receptor, IGF1 and IGF2 form a very potent axis of autocrine signalling that stimulates the proliferation of RMS tumours." (PMID 28793874, 2017). "This clinical data raises the hypothesis that IGF2 may have the ability, in part, to promote tumor growth via autocrine and/or paracrine mechanisms." (PMID 29099049, 2017). "However, IGF2 also binds to tumor cell surface IGF1R and IR, with preference for IR isoform A (IR-A)." (PMID 29099049, 2017). "The enrichment of IGF2PB3 in human malignancies might promote tumor growth via raising the quantity of IGF2." (PMID 28399871, 2017). "Tumor phenotype in Apc+/Min mice can be modified simply by altering the IGF2 epigenotype." (PMID 27275535, 2016). "In particular, IGFBPs and IGF2R provide two separate mechanisms to regulate IGF2 bioavailability and have each been suggested as a potential tumor suppressor; however, it remains unclear which plays the dominant role in regulating IGF2 activity in tumors." (PMID 26861122, 2016). "The tumor growth was significantly suppressed in the LV-miR-663b group when compared to that in LV-Control group, and the mRNA and protein levels of IGF2 were also down-regulated in LV-miR-663b group." (PMID 27895308, 2016). "Moreover, as our CETSA results show that compound 1 binds directly to IGF-1R β it is unlikely that alteration of IGF-2 in tumor cells is the primary mechanism of action of the compounds." (PMID 27384680, 2016). "We have shown that we can specifically target tumor cells in which IGF2 is biallelically expressed, and such targeting might prove to be a magic bullet to specifically kill the CSCs within a tumor." (PMID 27275535, 2016). "In patients with TNBC, progression of tumor cell populations may depend in part on complex interactions and the bioavailability of IGF-2 and ERβ." (PMID 25874233, 2015). "In this report, INSRs mediated NSCLC proliferation when only IGF-1R was blocked, suggesting that the resistant mechanisms to IGF-1R inhibitory agents may be the ability of tumor cell to switch from IGF-2/IGF-1R to IGF-2/INSR-A dependency." (PMID 26217584, 2015). "Clinical trials are warranted to assess whether therapeutic strategies targeting STAT3 or IGF-2 would circumvent tumour angiogenesis and pro-invasive consequences, overcoming innate resistance to anti-IGF-1R monoclonal antibody-based therapies." (PMID 26465273, 2015). "They stimulate gluconeogenesis and inhibit the big IGF2 tumor production." (PMID 24891941, 2014). "Our findings shed new light on the role of IGF2 in ACC tumor progression." (PMID 25089899, 2014). "Based on tissue culture experiments wherein transient IGF2 knockdown significantly decreased proliferation and cell viability, one might expect that IGF2 knockdown alone would decrease tumor growth of these cells in vivo." (PMID 24932685, 2014). "Other genetic aberrations such as insulin-like growth factor 2 dysregulation may be required for driving AC tumor cells towards a more malignant phenotype." (PMID 24755523, 2014). "Possibly will act as a tumor suppressor, influences growth via control of Igf2 expression." (PMID 24910706, 2014). "Recent studies revealed new molecular pathways by which IGF-2 confers androgen independent growth or can ignite the de novo steroidogenesis engine and promote molecular events associated with tumour progression evading hormone therapy." (PMID 25332874, 2014). "The concentration of IGF2 in the microenvironment of a particular tumor type may be critical to influence the effect of the increased IR-A/IR-B mRNA ratio." (PMID 24571613, 2014). "Big IGF2 may also account for elevated glucose consumption in the tumor by autocrine and paracrine effects." (PMID 24891941, 2014). "IGF2 has also a role in tumour cells migration and angiogenesis." (PMID 25225571, 2014).
tumor (continued). "Over-expression of IGF-2 in the tumor microenvironment was hypothesized as another potential mechanism of resistance." (PMID 23818948, 2013). "However, probably due to the small number of patients included in each subgroup, we were not able to find any significant correlation between the specific genetic alterations at the IGF2 locus and the clinical data (such as tumor size or stage)." (PMID 24066089, 2013). "Overexpression of the gene encoding IGF2 due to LOI/LOH observed in RMS has been implicated in both fetal overgrowth disorders that predispose children to embryonal tumors (including RMS) and RMS tumor cell growth and motility." (PMID 24350186, 2013). "Additive effects of Pten and Igf2 in pathway activation can also be modified, for example following titration of Igf2 dosage in Pten heterozygotes, resulting in corresponding titration of embryonic, placental and tumour phenotypes." (PMID 23468951, 2013). "We demonstrate that Wt1 ablation and Igf2 upregulation in tumors results in up-regulation of glucose utilization during initial stages of tumor development, followed by a gradual decrease in tumor glycolytic activity, consistent with the development of large areas of hemorrhagic necrosis." (PMID 22875335, 2013). "Furthermore, we also established thattumours with hits in Nfia, the CIS gene most frequently affected by SBinsertion, expressed Igf2 at higher levels than network tumours with noinsert in Nfia." (PMID 24252690, 2013). "Indeed, genetic studies in mouse, showed that Igf2 was dispensable at early pre-cancerous stages but that it was required at later stages of tumour progression." (PMID 22952916, 2012). "In summary, the 91H RNA could be assumed to be oncogenic by favouring Igf2 transcription while H19, which counteracts this effect, would act as a tumour suppressor." (PMID 22662250, 2012). "The grade of tumor pathology was higher, while the rate of IGF-2 gene expression was also higher." (PMID 22662119, 2012). "It is a commonly held view that increased circulating IGF2 is a tumor product." (PMID 23781309, 2012). "Interestingly, we recently discovered in human that an antisense H19 transcript, named the 91H RNA (or H19os for “H19 opposite strand” transcript), augments in trans the paternal IGF2 expression which is known to favour tumour progression." (PMID 22662250, 2012). "Finally, in a cohort of 38 HNSCC patient tumour samples, over-expression of Lin28b, IGF2BP2, and IGF2 were observed to be associated with worse clinical outcome, strongly suggesting a role for the Lin28b-IGF pathway in contributing to HNSCC relapse." (PMID 23482325, 2012). "This suggests that Igf2 overexpression may stimulate another essential process to accelerate tumour progression." (PMID 22952916, 2012). "The outcomes have shown that IGF-2 may play important role in the invasive growth and evolution of tumor." (PMID 22662119, 2012). "Recalling that EGF was downregulated and IGF-2 was strongly upregulated in tumor cells, the level of IGF-1R dysregulation may represent a switch that marks the onset of malignant transformation." (PMID 21464922, 2011). "Furthermore, the ligand of insulin and insulin-like receptors, IGF-2, was strongly upregulated in tumor cells, whereas there were moderate changes in transgenic cells (not detected by differential expression analysis)." (PMID 21464922, 2011). "Further evidence for this hypothesis was obtained when the gene expression of IGF2 and its down stream partners was investigated and determined to be highly significantly induced in tumour cells as were many components of this pathway." (PMID 21464922, 2011). "Notably, the Myb – COUP-TF pair was predicted in the promoter of the Igf2 gene, which was significantly upregulated in the tumor conditions." (PMID 21464922, 2011).
tumor (continued). "Thus, the simplest explanation for these observations is that there was mono-allelic expression of H19/IGF2 in the normal tissue, which was subsequently lost or allelically switched during tumor development." (PMID 20174472, 2010). "By that the targeted destruction of cancer cells expressing IGF2 or H19, companied by enhanced bystander effect, may lead to arrest of tumor growth and prevent following metastases process." (PMID 21162716, 2010). "The proportions of immunoreactive tumor cells varied between tumors and expression was regional with an abrupt onset at distances varying from 87 to 160 μm (median 115 μm) from the vascular stroma, which was strikingly coordinated with expression of IGF2." (PMID 20862257, 2010). "Tumor cells can express high levels of H19 and IGF2, or only one of those genes." (PMID 21162716, 2010). "Although IGF2 is downregulated in normal tissues after birth, except for liver tissues, it is overexpressed in a wide variety of childhood and adult cancers and serves as a tumour enhancer through autocrine and paracrine mechanisms." (PMID 19034281, 2008). "In addition, the paternal origin of the duplicated IGF2 loci was confirmed by the hypermethylated CTCF6 in 10 tumours with UPD." (PMID 19034281, 2008). "Our observation that knocking down H19 upregulates IGFBP4, which counteracts the tumor promoting activity of IGF2, could provide a link in trans between H19 and IGF2." (PMID 17786216, 2007). "In ROH tumours only, IGF2 LOI frequency occurred in approximately 56% of cases (14/25)." (PMID 16909133, 2006). "Decreased IGF2 and H19 mRNA levels were found in five (21%) and three (13%) tumours, respectively." (PMID 10944603, 2000). "The tumours expressed high levels of Igf-2 mRNA transcribed from the integrated transgenes." (PMID 7577466, 1995). "We observed that the downregulation of IGF2 could reduce tumor growth." (PMID 40271711, 2025). "However, experiments in mouse models suggest that IGF2 overexpression is not sufficient to trigger tumour development in the adrenal cortex, even in association with β-catenin activation." (PMID 40038716, 2025). "Indeed, IGF2 marker appears to hold a diagnostic value to identify ACC, although tumor functionality may influence its diagnostic performance." (PMID 39890749, 2025). "Moreover, IGF2-mediated suppression of immune cell activity contributes to tumor immune escape." (PMID 41465387, 2025). "Additionally, fibroblasts could also act as signal receivers, mediators, and influencers, interacting with C2 IGF2+ tumor cells." (PMID 39896800, 2024). "Moreover, the high expression of IGF2 might also be related to the maintenance of tumor stem cells, which had the ability to self-renew and differentiate into multiple lineages, and were one of the main reasons for tumor recurrence and drug resistance." (PMID 39896800, 2024). "In the C2 IGF2+ subtype, the expression level of IGF2 was typically higher, which might be related to its role in the proliferation and maintenance of stem cell characteristics in tumor cells." (PMID 39896800, 2024). "Additionally, a circle graph further confirmed that the interactions between C2 IGF2+ tumor cells and fibroblasts could be mediated through the receptor-ligand pairs within the MDK signaling pathway, specifically involving MDK-NCL." (PMID 39896800, 2024). "The tumor-suppressing effects of miR-491-5p on CRC cells might be reversed by upregulating IGF2." (PMID 37587156, 2023).
tumor (continued). "In addition to these, the accumulation of CAFs in tumor tissues can promote drug resistance by inducing the expression of insulin-like growth factor 2 (IGF2) and insulin-like growth factor receptor-1 (IGF-1R) signaling, which leads to P-glycoprotein expression and increased drug efflux." (PMID 37627173, 2023). "Thus, further research effort is needed to demonstrate whether high IGF2 may similarly program macrophages of the tumor environment." (PMID 36672737, 2023). "In addition, we used the same PS-based methods to assess the association between IGF2 methylation and CRC prognosis using CRC patient PBLs and tumour tissues, and then further validated our findings using external datasets from EPIC-Italy CRC cohort and The Cancer Genome Atlas (TCGA)." (PMID 37213278, 2023). "Additionally, increased IGF-2 levels in this tumor type contribute to increased angiogenesis." (PMID 35017650, 2022). "In addition to the suggestive IGF2 overexpression, which might also lead to cessation of cellular maturation in the developing liver, additional genetic alterations seem to drive tumor formation." (PMID 35804856, 2022). "While IGF2-linked hypoglycemia itself is not a predictor of tumor risk or aggressiveness, it might play a role in various tumor types." (PMID 34440844, 2021). "However, the multiplicity of tumor types and the long tumor latency suggest that IGF2 may act primarily as a tumor progression factor." (PMID 34440844, 2021). "However, IGF2 is commonly upregulated in cancer and secreted by a broad range of tumor cell types." (PMID 34440844, 2021). "IGF-1 and IGF-2 are mainly produced in the liver, although some of them can also be synthesized from other tissue such as kidney, brain, or neoplastic tissue, regulating normal physiological processes or tumor growth by autocrine, paracrine, and endocrine manners." (PMID 33429867, 2021). "Therefore, it would be informative to test whether inhibition of Igf2 signaling could suppress tumor formation in the Srsf2 HKO mice model in the future." (PMID 32372053, 2020). "Therefore, we provide physiological confirmation of the hypothesis that IGFs signaling in RCC is mediated mainly by circulating ligand proteins (IGF1 and IGF2) from sources other than RCC cancer tumor itself, as suggested before." (PMID 30929166, 2019). "Finally, the use of the off-target IGF1R inhibitor ceritinib may accelerate the development of clinical protocols for the treatment of tumor entities driven by IGF2 and IGF1R." (PMID 31234291, 2019). "IGF2 overexpression in neoplasms causes non-islet cell tumor hypoglycemia (NICTH)." (PMID 30168002, 2018). "Loss of IGF2 imprinting has also been observed in UCS tumor tissue 13, and nonislet cell hypoglycemia due to tumor production of incompletely processed forms of pro‐IGF2 (“big” IGF2) was previously reported in patients with UCS 14, supporting a potential, unrecognized role of IGF2 in UCS." (PMID 29455465, 2018). "Then, UBC could modulate STAT5A and CEBPA in the WNT and the MAPK signaling pathways to inhibit DNA repair through the dysregulation of HIST2H2BE and to induce the accumulation of autoimmune defects through the dysregulation of IGF2, which might ultimately facilitate tumor growth." (PMID 30344796, 2018). "Free IGF‐2 released from the complex may facilitate MSC migration toward tumor." (PMID 29321953, 2018). "Notably, IGF2 de-regulation cannot be assessed by merely probing the mutation landscape of the tumor, which renders scRNAseq of CTCs an outstanding tool to detect non-mutated druggable genomic aberrations such as IGF2 overexpression." (PMID 30068984, 2018).
tumor (continued). "As for H19, all tumor tissues except for one (ID 511) showed monoallelic expression, despite variation in iDMR methylation, strongly suggesting an absence of correlation between allelic expression of H19 and aberrant methylation of iDMRs within the IGF2/H19 domain." (PMID 30509319, 2018). "In addition, comparison of tumour size showed that presence of IGF2-pre-treated fibroblasts could drive tumour growth, and that Avastin treatment could abolish this effect." (PMID 28186102, 2017). "However, the localized ischemia and hypoxia brought about during TACE treatment can activate tumorigenic VEGF, IGF-2, and bFGF signaling pathways in some tumors, which can subsequently stimulate angiogenesis and the growth of residual tumor cells, leading to tumor recurrence and metastasis." (PMID 28938663, 2017). "Moreover, the tumor growth was also suppressed in the sh-HOTAIR group when compared to that in sh-Control group, and sh-HOTAIR group had higher expression level of miR-663b in the tumor than that in sh-Control group; also the mRNA and protein levels of IGF2 were down-regulated in sh-HOTAIR group." (PMID 27895308, 2016). "Furthermore, miR-216b downregulated the expression of insulin-like growth factor 2 mRNA-binding protein 2 (IGF2BP2) and exerted its tumor-suppressor function through inhibition of protein kinase B and extracellular signal-regulated kinase signaling downstream of IGF2." (PMID 25741595, 2015). "Thus, in the present case it seems, the proliferation of tumour cells might be rather supported by increased effect of IGF1, IGF2 and IGF1R homodimer associations, than IGF1, IGF2 and INSR-IGF1R heterodimer associations or INSR effects on IRS1." (PMID 25496518, 2014). "The genomic DNA of whole non-tumor mucosa was employed to screen for whether the samples were informative or not, using the PCR-based, IGF2 gene ApaI polymorphism." (PMID 25364428, 2014). "This may also be the case in NSCLC where IGF2 is known to support tumour growth." (PMID 23826179, 2013). "Furthermore, we successfully confirmed targeted tumor gene therapy based on IGF2 LOI." (PMID 23171475, 2012). "Although overexpression of Igf2 per se may have low oncogenic potential in transgenic mouse models, there is ample evidence that Igf2 can cooperate with other pathways to accelerate tumour progression." (PMID 22952916, 2012). "Interestingly, the effect of the 91H RNA on Igf2 derepression observed here in complementation studies, may explain the Igf2 derepression occurring in many tumours where 91H RNA was found to accumulate while the H19 gene is maintained in a repressed state." (PMID 22662250, 2012). "Thus, the high IGF2 mRNA expression of many HB tumours with ROI may mimic the upregulation of IGF2 expression in embryonic liver tissues, from which HB may arise." (PMID 19034281, 2008). "Because 20–30% of HB tumours do not respond to the current chemotherapy consisting of cisplatin and adriamycin, and the great majority of HB tumours overexpresses IGF2, as shown in the present and earlier studies, HB may be the next target tumour for antibody therapy." (PMID 19034281, 2008). "Our results showed that the genetic and epigenetic alterations in the IGF2-H19 region with elevated expression of IGF2 mRNA identified in WTs were also found in the great majority of HB tumours, although the incidences of LOH and LOI may be lower in HBs than in WTs." (PMID 19034281, 2008). "Thus, biallelic hypermethylation leading to IGF2 LOI occurred in 11 tumours with ROH." (PMID 16909133, 2006). "In addition H19 RNA may suppress IGF2 expression in trans and has tumour suppressor functions in cell transfection studies." (PMID 15885138, 2005). "IGF2 was identified early after the discovery of GBM stem cells as a stemness-promoting factor, but its role in fueling a tumor-promoting microenvironment is only recently becoming apparent." (PMID 41568176, 2026).